HMGB1 (high mobility group box 1)
Diseases named in the same sentence as HMGB1 in open-access papers (continued):
Sharing a sentence is not in itself a finding about the gene and the disease.
Sepsis (continued). "Disruption of Notch signaling by DAPT attenuated the LPS-induced inflammatory responses, including vascular endothelial growth factor (VEGF) and high-mobility group box chromosomal protein 1 (HMGB1), both in vitro and in vivo and partially improved experimental sepsis survival." (PMID 21843347, 2011). "For instance, HMGB1 can activate immune cells to produce various cytokines and chemokines, thereby sustaining a potentially injurious inflammatory response in sepsis." (PMID 21347455, 2011). "Consistently, anti-HMGB1 antibodies or inhibitors (e.g., tanshinones, ethyl pyruvate, nicotine, stearoyl lysophosphatidylcholine, or epigallocatechin-3-gallate) confer protection in animal models of endotoxemia and sepsis." (PMID 21347455, 2011). "Consequently, as increased HMGB-1 serum levels were shown to reflect adverse outcome from sepsis also, targeting of this late proinflammatory mediator was proposed." (PMID 20652004, 2010). "Whereas the findings in regard HMGB1 were inconsistent in identification of patients with infections and those without, IL-6 has been suggested to be a suitable early inflammatory marker, with levels correlating well with the severity and prognosis of sepsis." (PMID 20158885, 2010). "In the past, however, it was debated whether the “late mediator” HMGB-1 reflects monocytic immunity and whether this may guide immunomodulatory interventions in sepsis." (PMID 20652004, 2010). "In the present analysis, we aim to investigate the “in vivo interplay” between monocytic function (assessed using monocytic HLA-DR expression [mHLA-DR] and ex vivo TNF-alpha release) and HMGB-1 serum levels in patients with severe sepsis/septic shock and sepsis-induced immunosuppression." (PMID 20652004, 2010). "HMGB1 is a constitutive intracellular protein that is released into the extracellular milieu from damaging cells in response to the inflammation during hemorrhage or sepsis." (PMID 20628562, 2010). "Indeed, ethyl pyruvate, stearoyl lysophosphatidylcholine, and nicotine have been shown to be efficacious in ameliorating experimental sepsis by preventing HMGB1 release during experimental sepsis." (PMID 20706656, 2010). "HMGB1 appears to be an early mediator of the sterile inflammation induced by trauma-hemorrhage; in contrast, the kinetics of HMGB1 release due to sepsis may differ depending on the primary source of infection." (PMID 19887013, 2009). "Taken together, these results indicate that HMGB1 is a late mediator of sepsis that has an important mechanistic role in that disease, because the inhibition of HMGB1 activity significantly ameliorates the survival in experimental animal models of septic shock." (PMID 19887013, 2009). "Importantly, neutralizing the effects of HMGB-1 at this late time point, either by anti-HMGB-1 antibodies or antagonists, rescued mice from sepsis-induced mortality." (PMID 19841752, 2009). "The interest for this late release of HMGB1 after exposure to LPS was related to the fact that an anti-HMGB1 blocking antibody could rescue mice from lethality after cecal ligation and puncture as late as 24 hours after the beginning of sepsis." (PMID 19887013, 2009). "Data from experimental sepsis models show that administration of anti-HMGB1 antibodies significantly decreased mortality, even when administration was delayed for 24 hours, providing a window of opportunity for therapeutic intervention if transferred into a clinical setting." (PMID 18577209, 2008). "In experimental murine models of endotoxemia and sepsis, administration of anti-HMGB1 antibodies decreased mortality significantly, even when administration was delayed for 24 hours, providing a window for therapeutic intervention if transferred into a clinical setting." (PMID 18577209, 2008). "Furthermore, successful HMGB1-targeted therapies in experimental sepsis, arthritis and brain ischaemia strongly down-regulate in vivo synthesis of TNF." (PMID 18346273, 2008).
Sepsis (continued). "In addition, studies have shown that HMGB1 is an important late mediator of inflammation and acute lung injury in sepsis." (PMID 18380908, 2008). "Two polymorphisms were determined as significant risk factors associated with early and late mortality, which may provide insight into the molecular background of SIRS and sepsis, suggesting a possible role for HMGB1 genetics in future prognostic evaluation." (PMID 18577209, 2008). "Using a lipopolysaccharide (LPS) sepsis model in rats, we demonstrate that danaparoid sodium (50 U/kg) can reduce pulmonary histopathology, decrease mortality, and diminish inflammatory mediators and high mobility group box 1 (HMGB1) serum and lung levels." (PMID 18380908, 2008). "The mean serum HMGB1 levels tended to increase when moving from patients with only SIRS to patients with sepsis of increasing severity, although only reaching a near-significant level (P = 0.08) when comparing SIRS patients with sepsis patients regardless of severity." (PMID 18577209, 2008). "For the moment we can only point out the presence of HMGB1 at a significant concentration (10 ng/mL) in the serum of a healthy control, and the undetectable levels of HMGB1 in the serums of some patients with sepsis." (PMID 18682735, 2008). "HMGB-1, also a DNA-binding protein, is released from cells due to necrosis or via a non-classical secretion pathway and is a late-stage mediator of lethality in a murine model of sepsis." (PMID 18042296, 2007). "Indeed, apoptotic cells have been shown to enable HMGB-1 release by activated macrophages in a sepsis model." (PMID 17520028, 2007). "HMGB1 levels have been measured in several clinical sepsis cohorts." (PMID 17625012, 2007). "Therefore, we propose that EGCG rescues mice from lethal sepsis partly through inhibiting systemic HMGB1 accumulation, as well as HMGB1-induced release IL-6 and KC." (PMID 17987129, 2007). "These correlations seem to confirm a proinflammatory role for HMGB1 in human sepsis." (PMID 17625012, 2007). "Notably, these anti-HMGB1 reagents are capable of rescuing mice from lethal experimental sepsis even when the first doses are given 24 h after the onset of the disease, indicating a wider window for HMGB1-targeted therapeutic strategies." (PMID 17987129, 2007). "Further studies are needed to elucidate the role of HMGB1 in the immunopathogenesis of sepsis." (PMID 17346334, 2007). "Animal models have shown that HMGB1 has an important role in immunopathogenesis in sepsis." (PMID 17625012, 2007). "In addition, it was shown that protection against sepsis was attributed to the high mobility group box-1 (HMGB-1) protein, which was significantly diminished upon nicotine treatment." (PMID 16480493, 2006). "In vivo increased levels of HMGB-1 are shown in patients with severe sepsis." (PMID 16759367, 2006). "In contrast to early inflammatory mediators, HMGB1 plays a pivotal role as a late inflammatory mediator capable of activating intracellular NF‐κB signaling pathway and exacerbating tissue damage; thus making it an important target for preventing and treating late‐stage sepsis." (PMID 41551210, 2026). "HMGB1 is a non-histone nucleoprotein that is strongly associated with sepsis." (PMID 41463300, 2025). "After release to the extracellular space, HMGB1 acts as a damage-associated molecular pattern molecule (DAMP) that critically mediates inflammation and immune responses in various conditions, including sepsis, atherosclerosis, arthritis, neurodegeneration, meningitis, and cancer." (PMID 40804938, 2025). "Furthermore, in the plasma mitochondrial DNA, a potent DAMP, the copy number was highly correlated with the essential necroptosis mediators, including RIPK3, MLKL and HMGB1, suggesting that mitochondrial DNA propagates necroptosis and increases the mortality rate due to sepsis in our previous study." (PMID 40318009, 2025).
Sepsis (continued). "Furthermore, lactate has been shown to promote the lactylation and acetylation of high mobility group box-1 (HMGB1) in macrophages during polymicrobial sepsis, suggesting a synergistic role of lactylation and acetylation in modulating immune responses and inflammation." (PMID 40867622, 2025). "Thus, suppressing AM pyroptosis and HMGB1 secretion could serve as a therapeutic approach to mitigate ARDS in sepsis." (PMID 40599023, 2025). "Clinical research shows that HMGB-1 can be secreted passively by injured and necrotic cells or actively by activated immune cells under the stimulation of cytokines, while it can also be released in large quantities in various pathological processes such as sepsis, tumours, infections, and shock." (PMID 40821625, 2025). "HMGB1 plays a multifaceted role in the progression of various diseases, including its involvement in promoting malignant tumor phenotypes, suppressing anti-tumor immunity by hampering the monocyte system, and triggering an inflammatory cytokine storm in sepsis." (PMID 38731953, 2024). "Thus, our results indicate that CGK012 may be a promising agent for modulating the early phase of sepsis by inhibiting HMGB1 secretion." (PMID 38474222, 2024). "HMGB1 may contribute to the persistence of inflammatory responses, making it a target for therapeutic intervention in conditions characterized by chronic inflammation, as seen in sepsis." (PMID 38920613, 2024). "Therefore, HMGB1 plays a pivotal role in various infectious diseases, cancer progression, neurodegenerative disorders, autoimmune diseases, and inflammatory disorders, including sepsis." (PMID 38187250, 2024). "Notably, within the PPI network analysis, key proteins including ICAM1, Resistin, TIMP1, VWF, CRP, and HMGB1 were identified at the central nodes of the network module, revealing a significant difference (P < 0.05) between the normal group and the sepsis group." (PMID 38951753, 2024). "In addition, the markers of necroptosis RIPK1, RIRK3, and MLKL and the HMGB1 released by necroptosis in peripheral blood of septic patients were significantly increased and positively correlated with the severity and mortality attributed to sepsis." (PMID 38816685, 2024). "Hence, targeting HMGB1 may modulate the inflammatory response and improve outcomes in patients with sepsis." (PMID 38474222, 2024). "Similarly, macrophages could also enhance the uptake of extracellular lactate via MCT during polymicrobial sepsis with elevated lactate levels and promote the lactylation of HMGB1 dependent on the “writer” p300/CBP." (PMID 38200523, 2024). "Additionally, HMGB1 plays a crucial role in mediating delayed endotoxin lethality and is indispensable for the complete manifestation of inflammation in animal models of endotoxemia, sepsis, and arthritis." (PMID 38510969, 2024). "By enhancing the SIRT1-mediated deacetylation of HMGB1, CGK012 may mitigate the damaging effects of HMGB1 on the vascular barrier, highlighting its therapeutic potential in pathological vascular inflammation associated with conditions such as sepsis." (PMID 38474222, 2024). "However, it remains uncertain whether YTHDF2 affects HMGB1 release and whether the impact of YTHDF2 on HMGB1 release is connected to the regulation of the IL-6R/JAK2/STAT1 pathway in sepsis." (PMID 38026444, 2023). "Several DAMPs, such as HMGB1, histones, extracellular cold-inducible RNA-binding protein (eCIRP), and heat shock proteins (HSPs), are recognized as critical inflammatory mediators that initiate and potentiate inflammation and can lead to organ dysfunction or death in sepsis." (PMID 36865384, 2023). "Hmgb1 was initially included in this cohort of candidate DEGs, as it has been shown to be a mediator of neuroimmune responses in many divergent clinical conditions including sepsis, atherosclerosis, cancer, and alcohol use disorder, as well as chronic pain at the peripheral and spinal levels." (PMID 37569320, 2023).
Sepsis (continued). "In addition, calycosin also alleviates sepsis-induced acute lung injury by inhibiting the HMGB1-myeloid differentiation primary response protein 88 (MyD88)-nuclear factor-κB (NF-κB) pathway and NOD-like receptor thermal protein domain associated protein 3 (NLRP3) inflammasome." (PMID 37403077, 2023). "HMGB1 could be one of the causes of the damage since it can initiate and perpetuate neuroinflammation during sepsis without direct injury to the CNS." (PMID 37569277, 2023). "Finally, BMSC-exos ameliorated the mortality rate, AECII apoptosis, inflammatory cytokine storm including HMGB1 and IL-6, and pathological lung damage in sepsis mice, which also could be prevented by ML385." (PMID 37035447, 2023). "Notably, HMGB1 is a late mediator of inflammation in sepsis." (PMID 36906561, 2023). "Compare with the early inflammatory factors, HMGB1 appears later and lasts longer, and its function is not limited to the simple pro-inflammatory response, but also closely relates to the cellular immune dysfunction of the body, suggesting that HMGB1 intervention may contribute to sepsis." (PMID 35720285, 2022). "Interestingly, ongoing research ex vivo and in different mouse models links oxidized HMGB1 to angiogenesis in cancer, depression due to neuroinflammation and sepsis, by increasing cell metabolism and the release of pro-inflammatory cytokines—two hallmarks of sepsis." (PMID 35740078, 2022). "miR-103a-3p could attenuates sepsis-induced liver injury by targeting HMGB1." (PMID 35720285, 2022). "However, the role of exosomal HMGB1 in sepsis pathogenesis is unclear." (PMID 34363018, 2022). "Similarly, in a mouse model of sepsis, accumulation of HMGB1 in the late phase of sepsis contributes to neutrophil defects and may be responsible for increased susceptibility to secondary infections." (PMID 36010680, 2022). "The interplay between complement and HMGB1 could likely play a key role in several other severe disease contexts, in particular inflammatory diseases where the immune pathology is host-driven, including cancer, sepsis, senescence." (PMID 35572583, 2022). "However, whether these cytokines, together with HMGB1, also affect the frequency of CD19hiFcγRIIbhi B cells in peripheral blood of patients with sepsis needs to be investigated further." (PMID 35983056, 2022). "To examine whether HMGB1 could be carried by circulating exosomes during sepsis, we collected blood samples from sham control and septic mice treated with or without supplemental lactate and measured HMGB1 levels by ELISA in the serum with and without exosome depletion." (PMID 34363018, 2022). "For example, the release of mitochondrial DNA and damage-associated molecular patterns (DAMPs) following injury, trauma or sepsis (especially within ECs) has been implicated in activating TLR9, inducing MAPK and NF-κB inflammatory pathways and disrupting the EC barrier via the targeting of HMGB1." (PMID 35955534, 2022). "Anti-brain HMGB1 could improve dendritic cell dysfunction in sepsis mice." (PMID 35720285, 2022). "acteoside reduces HMGB1 release and may be beneficial for the treatment of sepsis." (PMID 35720285, 2022). "Furthermore, the overexpression of miR-22 can reduce the expression of inflammatory factors (IL-1β, IL-6, and TNF-α) and NO, as well as significantly reduce cell apoptosis via PTEN/high-mobility group Box 1 (HMGB1) and TLR4/NF-κB pathway, thereby alleviating the AKI caused by sepsis." (PMID 35464083, 2022). "LncRNA GAS5 might through HMGB1 and subsequent NF-κB promote sepsis-induced myocardial inhibition." (PMID 35720285, 2022). "Therefore, inhibition of the translocation and release of HMGB1 can potentially prevent liver injury during sepsis and may provide a wider treatment window." (PMID 35222035, 2022).
Sepsis (continued). "Interestingly, sodium butyrate, a deacetylase inhibitor, which conveys a protective effect in certain inflammatory diseases, such as sepsis and lipopolysaccharide-induced acute lung injury, can also reduce hepatic granulomas and fibrosis induced by S. japonicum by inhibiting HMGB1 expression." (PMID 35335612, 2022). "Besides high-mobility group box-1 (HMGB1), a damage associated molecular pattern (DAMPs), is also released to the circulation during the development of sepsis and phytochemicals targeted on this pathway are of high interest for their potential use in sepsis management." (PMID 36588685, 2022). "In sepsis, a great amount of pro-inflammatory cytokines and damage associated molecular patterns (DAMPs) released, including tumor necrosis factor-α (TNF-α), interleukin (IL) family and high mobility group box 1 (HMGB1) which lead to further organ dysfunction and multiple cell death." (PMID 34867376, 2021). "The results support the hypothesis of necroptosis as a mechanism of an HMGB1 shift in sepsis." (PMID 33947887, 2021). "Increasing evidence indicate that extracellular HMGB1 released from the cell could act as an inflammatory signal to elicit inflammation and immune response and participate in the late-stage pathogenesis of sepsis." (PMID 33128580, 2021). "In addition, it remains to be investigated whether other derivatives of 8-HQ have similar effects on the inhibition of HMGB1/LPS-mediated caspase-11 signaling and the corresponding organ dysfunction and death in sepsis." (PMID 34093202, 2021). "Therefore, type I IFN and HMGB1 has been seen as the potential therapeutic target in sepsis." (PMID 34674749, 2021). "However, the association of the plasma levels of HMGB1 with necroptosis in sepsis has not been investigated." (PMID 33947887, 2021). "HMGB1, released to the bloodstream during the initial inflammatory cascade, has been postulated as a pro-inflammatory cytokine that could serve as an early biomarker in sepsis." (PMID 34576097, 2021). "The ICV injection of BoxA showed no significant influence in DC function at sepsis 24 h, while reversed its inhibited activation at 48 h after sepsis induction, suggesting that persistent release of brain HMGB1 could be detrimental to the immune response of DCs." (PMID 34512319, 2021). "Therefore, targeting HMGB1/RAGE may be a potentially effective strategy for clinical therapy in sepsis." (PMID 34747306, 2021). "To date, molecules such as HMGB1 and bacterial outer membrane vesicles that are required for localization of LPS in cytosol might have taken advantage on this immune-thrombotic mechanism in triggering systemic coagulation during sepsis." (PMID 34824200, 2021). "Interestingly, PARP1 has been demonstrated to promote the secretion of HMGB1 in sepsis." (PMID 34410682, 2021). "Thus, this study clearly suggests that the HMGB1–caspase-11 pathway is a potential drug target in lethal immune disorders and might open a new avenue in the treatment of sepsis." (PMID 34093202, 2021). "Therefore, antagonizing HMGB1 in serum or intervening in the pathway of HMGB1 mediated pro-inflammatory pathways may facilitate development of potential therapies in sepsis." (PMID 33552058, 2020). "Whether HMGB1 plays the same role in sepsis is question that requires additional investigation." (PMID 33552058, 2020). "In this study, we have shown that SGC-CBP30 attenuated circulating HMGB1 levels even when the treatment was started at 8 h after sepsis modeling, and that HMGB1 induced the release of TNF-α, suggesting that CBP bromodomain might function as a regulator in controlling HMGB1." (PMID 33603756, 2020). "Anti-HMGB1 antibodies or inhibitors (e.g., ethyl pyruvate, nicotine, stearoyl lysophosphatidylcholine and Chinese herbs such as Angelica sinensis) protects mice against lethal endotoxaemia, and rescues them even when the first doses are given 24 h after onset of sepsis." (PMID 32629817, 2020).